NLRP3 (NLR family pyrin domain containing 3)
Diseases named in the same sentence as NLRP3 in open-access papers (continued):
Sharing a sentence is not in itself a finding about the gene and the disease.
Sepsis (continued). "The same research group later showed that treatment of CLP mice with a specific NLRP3 inflammasome inhibitor (MCC950) significantly attenuated platelet activation and multi-organ damage induced by sepsis." (PMID 37108623, 2023). "These natural small-molecule compounds can modulate many signaling pathways, such as NF-κB, TLR4, MAPK, NLRP3, AMPK, and PI3KAKT, to prevent and treat sepsis." (PMID 37628912, 2023). "Exploring the mechanism of mitochondrial regulation of NLRP3 inflammasome activation in cardiomyocytes during sepsis leading to myocardial injury and the method of restoring mitochondrial function may provide new ideas for the clinical treatment of myocardial injury in sepsis." (PMID 37904696, 2023). "It was found that patients with sepsis and ARDS had higher serum NLRP3 concentrations at baseline in patients who died at 28-day follow-up (p<0.001), and the baseline serum NLRP3 levels had a significant predictive value for 28-day death (p<0.001)." (PMID 37649483, 2023). "Activation of bile acid receptors FXR and TGR5 altered the NLRP3 inflammasome and cAMP/PKA/CREB signaling to decrease sepsis." (PMID 37508557, 2023). "As a late‐phase alarmin in sepsis, HMGB1 interacts with RAGE to deliver cytosolic LPS, consequently activating the NLRP3 inflammasome in murine macrophages and lung ECs, leading to caspase‐11‐dependent pyroptosis." (PMID 38020710, 2023). "In a murine model of sepsis by cecum ligation and puncture (CLP) and in lipopolysaccharide(LPS)‐induced cardiac fibroblasts, corticosteroid pretreatment was found to inhibit NLRP3 formation, cysteine asparaginase‐1 activation, and IL‐1β secretion." (PMID 37904696, 2023). "In experimental peritonitis or acute liver injury during sepsis, MSC administration decreased NLRP3 inflammasome activation and NF-κB signaling in the damaged tissue, probably through the release of PGE2 in response to the inflammatory milieu." (PMID 37533852, 2023). "Since ATP plays an essential role as an extracellular signaling molecule in the development of sepsis and septic organ failure, we focused on the mechanism of S1PR3 in ATP-induced NLRP3 inflammasome activation in our research." (PMID 36798132, 2023). "The expression of NLRP3, Caspase-1, GSDMD, IL-1β, and IL-18 was decreased, suggesting that ALDH2 also inhibited pyroptosis in sepsis-induced lung injury." (PMID 35188436, 2022). "Treatment of CLP-mice with ICOS-Fc also attenuated the sepsis-induced local activation of FAK, P38 MAPK and NLRP3 inflammasome." (PMID 36119089, 2022). "Based on the results obtained in the current study, a conclusion is reached that YTHDF1 promotes NLRP3 ubiquitination by upregulating WWP1, thereby inhibiting caspase-1-dependent pyroptosis, which contributes to attenuation of sepsis." (PMID 35508474, 2022). "In conclusion, our results indicated that NC supplementation for 10 days in ICU patients with sepsis significantly decreased pro-inflammatory cytokines, MODS, and SOFA scores, the mRNA expression of NF-êB, NLRP-3, IFN-γ, and increased the expression of FOXP3." (PMID 36562037, 2022). "Transcription factors can therefore regulate pyroptosis in sepsis, especially SAOD, including its stimulation signals and the priming, activation, and assembly of the NLRP3 inflammasome." (PMID 35967871, 2022). "The knockout of NLRP3 or inhibition of its activation significantly reduces the release of inflammatory mediators, decreases multiple organ failure (MOF) in sepsis, and improves the survival rate of sepsis." (PMID 35847986, 2022). "Nifuroxazide can reduce sepsis-related ALI and myocardial injury by inhibiting the NLRP3 inflammasome activation and reducing the inflammatory mediator secretion." (PMID 35720321, 2022). "In conclusion, MIF plays an effect of renal damage in sepsis-induced AKI, up-regulation of MIF in response to LPS stimulation promotes phosphorylation of p65 and finally aggravated NLRP3 inflammasome mediated cell pyroptosis." (PMID 35165294, 2022).
Sepsis (continued). "Of note, the upregulation of NLRP3, cleaved caspase-1 and cleaved GSDMD that are related to caspase-1-dependent pyroptosis was found in pneumonia-induced sepsis." (PMID 35508474, 2022). "calycosin alleviates sepsis-induced ALI in young rats by inhibiting the HMGB1/MyD88/NF-κB pathway and NLRP3 inflammasome activation." (PMID 35720285, 2022). "The present study aimed to evaluate the modulation of NLRP3 activity by administering MFA and its implications in reducing inflammatory parameters, mitochondrial and oxidative damage in the early stages of sepsis." (PMID 36333747, 2022). "Furthermore, activation of NLRP3 inflammatory corpuscles could promote AKI induced by sepsis." (PMID 35428927, 2022). "To clarify the NLRP3 inflammasome activation in sepsis, we performed CLP on mice to observe the NLRP3 inflammasome expression in lung tissue." (PMID 35720321, 2022). "NLRP3, caspase-1, and ASC have been exploited as new therapeutic targets against pyroptosis and sepsis." (PMID 36077522, 2022). "In genetic depletion of genes encoding for Pink and Park2, a subsequent decrease in neurotransmitter dopamine was accompanied with increase of late sepsis mediator—HMGB1, via mechanism of HIF-1α-dependent anaerobic glycolysis and NLRP3 inflammasome activation." (PMID 34824200, 2021). "LBH alleviated lung injury in sepsis-induced ALI mouse model by inhibiting inflammation and NLRP3 inflammasome, and restrained the inflammation by inhibiting NLRP3 inflammasome in LPS-induced A549 cells, providing a novel therapeutic target for ALI." (PMID 33553423, 2021). "Phosphorylation of serine 5 in the PYD inhibits the activation of NLRP3.Sequential ubiquitination of NLRP3 by RNF125 and Cbl-b inhibits the activation of NLRP3 and prevents the development of sepsis in mice." (PMID 34745104, 2021). "In this study, we evaluated LBH expression in sepsis-induced ALI mouse model and explored the regulatory effects of LBH on lung injury, inflammation, and NLRP3 inflammasome activation." (PMID 33553423, 2021). "NLRP3, which belongs to the NLR family, plays a vital role in sepsis-induced myocardial dysfunction." (PMID 34820388, 2021). "The results showed that the levels of caspase-11, GSDMD-NT, NLRP3, ASC, caspase-1, IL-1β, and IL-18 were increased in sepsis mice and that ST pre-treatment suppressed this effect." (PMID 34483936, 2021). "In polymicrobial sepsis induced by cecal ligation and puncture (CLP), inhibiting the activity of CASP1 with the NLRP3 inhibitor MCC950 also reduces platelet activation in rats." (PMID 33796108, 2021). "Here, we found that the serum-derived EVs of sepsis patients and macrophages contain high levels of HMGB1 and stimulate the activation of the NLRP3 inflammasome and liver damage." (PMID 34743181, 2021). "LPS was utilized to induce sepsis and lung injury in C57BL/6 or NOD-like receptor family pyrin domain containing 3 (NLRP3)−/− mice." (PMID 33549095, 2021). "The colocalization of the NLRP3 and ASC proteins was higher in the sepsis group than in the sham group and was markedly increased in the SESN2−/− septic mice compared to WT septic mice." (PMID 34741186, 2021). "Sepsis patients exhibited significantly higher expression and production of NLRP3 and the proinflammatory cytokines (TNF-α, IL-6 and IL-1β) than healthy controls, and these levels were significantly increased with sepsis progression." (PMID 34172780, 2021). "Here we explored the possible roles of RDV in sepsis-induced AKI, especially focusing on its roles in NLRP3 inflammasome activation, to identify a novel approach for inflammatory disease treatment." (PMID 34093539, 2021). "Thus, NLRP3 could be a promising molecular target for sepsis-induced AKI treatment." (PMID 32626733, 2020). "pneumoniae, NLRP3 increases the incidence of ALI and mortality due to the bacterial dissemination and the development of the sepsis." (PMID 32849610, 2020).
Sepsis (continued). "The findings of this study demonstrated that the sepsis group with GLN administration exhibited increased gene expressions of caspase-11 and NLRP3 in the liver at 24 h post-CLP." (PMID 32295272, 2020). "The findings suggest that intravenous Arg supplementation immediately after sepsis restores plasma Arg levels and is beneficial for attenuating septic AKI, partly via NO-mediated NLRP3 inflammasome inhibition." (PMID 32454788, 2020). "The TLR4 inhibitors, eritoran, polyamidoamine, and tak-242, have been shown to decrease the inflammatory response in sepsis animals, and the NLRP3 inhibitor, MCC950, has been shown to have a positive effect in sepsis mice." (PMID 33324236, 2020). "It is important to note that mtDNA cannot only be sensed by NLRP3, but also by multi-signaling pathways, such as TLR9 and cyclic GMP-AMP synthase, to induce the progression of sepsis." (PMID 33324236, 2020). "Recent studies demonstrate that NLRP3 inflammasome-related molecules (e.g., NLRP3 and ASC) are critically involved in the acute inflammation and tissue injury involved in the pathogenesis of CLP-induced polymicrobial sepsis." (PMID 32648582, 2020). "Since the animals showed enhanced inflammation, which was probably mediated via NLRP3-inflammasome signalling and via complement activation, the effects of CLP sepsis on cardiac structure proteins were determined in left ventricles by microscopy." (PMID 32410859, 2020). "Taking these findings together, rGRA9C increases the anti-inflammatory and bactericidal effects through interacting with NLRP3 in CLP-induced and bacterial-induced sepsis model mice." (PMID 33182702, 2020). "Both 15-lipoxygenase metabolites 13-HODE and 13-HOTrE are able to inhibit the NLRP3 inflammasome complex and increased levels of 13-HODE were also discovered in patients suffering from sepsis." (PMID 33117382, 2020). "Most importantly, MCC950 or Ac-YVAD-CMK treatment prevented sepsis-induced neuronal damage and cognitive deficits in CLP mice, suggesting that the NLRP3/caspase-1 pathway is involved in the neurotoxicity and cognitive impairments observed in SAE." (PMID 30276509, 2019). "Our study demonstrated that the activation levels of NF-κB (p65), pro-caspase-1, pro-IL-1β, NLRP3, caspase-1 and IL-1β were increased after CLP/LPS+ATP, illustrating that the NLRP3/caspase-1/IL-1β signaling pathway participates in sepsis." (PMID 30779706, 2019). "S194A-mutant NLRP3 expressed in mice prevented both MSU-induced peritonitis and LPS-induced sepsis through inhibition of NLRP3 inflammasome activation." (PMID 29868015, 2018). "Further supporting the immunosuppressive role of mitophagy in sepsis, a recent study showed that senstrin 2 (SESN2) restrains NLRP3 activity by promoting the elimination of damaged mitochondria in macrophages." (PMID 29951054, 2018). "Accumulated evidence show that the NLRP3 inflammasome also mediates the release of high mobility group box 1 (HMGB1), a late mediator of lethal sepsis, and contributes to the pathogenesis of septic shock." (PMID 30134814, 2018). "The present study provides a basis for the use of CORM-2 as an effective strategy to protect against sepsis-induced AKI, and exogenous CO as released by CORM-2 treatment decreases the oxidative stress and NLRP3 inflammasome activation." (PMID 26334271, 2015). "The purpose of the present study was to explore the effects of exogenous CO on sepsis-induced AKI and nucleotide-binding domain-like receptor protein 3 (NLRP3) inflammasome activation in rats." (PMID 26334271, 2015). "The dysregulated NLRP3 activation is a critical mechanism in several serious neonatal diseases characterized by intense inflammation, such as hypoxic–ischemic encephalopathy (HIE), bronchopulmonary dysplasia, sepsis, and necrotizing enterocolitis." (PMID 41149694, 2025). "Therefore, calycosin can attenuate sepsis-induced acute lung injury by inhibiting the HMGB1/MyD88/NF-κB pathway and NLRP3 inflammasome activation." (PMID 41463300, 2025).
Sepsis (continued). "The administration of MCC950, a highly potent and specific inhibitor of NLRP3, effectively blocked YOD1-mediated coagulation in MRSA-induced sepsis, thereby supporting the role of YOD1 in regulating NLRP3 inflammasome-dependent coagulation during MRSA-induced disseminated intravascular coagulation." (PMID 40867920, 2025). "The 3 main mechanisms of endothelial pyroptosis in sepsis include the GSDMD-NT (gasdermin D N-terminal domain)-dependent pathway, the NLRP3 (nucleotide-binding domain, leucine-rich-containing family, pyrin domain-containing-3)-dependent pathway, and intercellular communication." (PMID 41280722, 2025). "When sepsis evaluation is negative in a neonate with multisystem involvement, alternative considerations include monogenic autoinflammatory disease (e.g., NLRP3/NOMID, NLRC4), primary immunodeficiency, inborn errors of metabolism, and congenital leukemia." (PMID 41477640, 2025). "Our study uncovers a role for RIPK3/caspase-8 signaling in regulating obesity-induced inflammation, independent of its capacity to activate NLRP3, aligning with recent reports in sepsis and arthritis models." (PMID 39532538, 2025). "Experimental models have demonstrated that genetic ablation of inflammasome components—such as NLRP3, caspase-1, caspase-11, or GSDMD—confers protection against sepsis-induced mortality by attenuating systemic inflammation, coagulopathy, and multiorgan dysfunction." (PMID 40558557, 2025). "Notably, inflammasome pathways such as the NLRP3 inflammasome, along with NF-κB, JAK-STAT, MAPK, and cGAS-STING pathways, play central roles in the intracellular signal transduction responsible for sepsis and SIC." (PMID 40649892, 2025). "It activates inflammasomes, such as absent in melanoma 2 (AIM2) and NLRP3, to promote the release of IL-1β and IL-18, enhance pathogen clearance, and modulate inflammation, particularly in sepsis and endotoxemia." (PMID 40788157, 2025). "Remarkably, NF-κB, NLRP-3, Caspase-1, and GSDMD C-NT revealed considerable dose-dependent expression downregulation in response to CLM indicating its anti-pyroptotic effect during sepsis-induced liver dysfunction." (PMID 40770673, 2025). "In this context, disruption of TLR sensing or conformational activation of NLRP3, GSDMD, STING, or other related pathways may influence sepsis progression." (PMID 40461967, 2025). "Similarly, studies have indicated that the use of P2X7R antagonists mediates the inactivation of NLRP3 inflammasome and treats IRI and sepsis-induced AKI." (PMID 40709185, 2025). "In a cecal ligation and puncture (CLP)-induced sepsis rat model, calycosin treatment was shown to decrease the levels of HMGB1, MyD88, p-NF-κB, and NLRP3, as well as the contents of pro-inflammatory cytokines such as TNF-α and IL-1β, at the significantly effective dose of 50 mg/kg." (PMID 41463300, 2025). "In addition, the Ca2+ channel inositol 1,4,5-trisphosphate receptor type 2 is required for NLRP3 inflammasome activation and GSDMD-triggered pyroptosis in the context of sepsis-induced cardiomyopathy." (PMID 40307577, 2025). "The NLRP3 inflammasome, a characteristic member of the NLR family, has been shown in numerous studies to be activated in response to reactive oxygen species during sepsis." (PMID 40070882, 2025). "SRPK1 overexpression can promote cell proliferation, inhibit apoptosis in primary human pulmonary microvascular endothelial cells, and alleviate sepsis-induced ALI in vivo through forkhead box O 3-mediated transcriptional inactivation of NLRP3 and inhibition of NLRP3 mRNA and protein expression." (PMID 38716051, 2024). "Western blot analysis revealed that in the LPS-induced sepsis model (Group 2), Nogo-A expression was significantly elevated, while the expression of proteins such as p-PERK, MFN1, NOX2, NOX4, NLRP3, p-STING, p-TBK1, and IL-1β also significantly increased, and SHP2 expression decreased." (PMID 39151100, 2024).
Sepsis (continued). "The protein levels of pyroptosis markers, including NLRP3, caspase-1 p20 and GSDMD-N, were suppressed by BRD3308, which indicated that BRD3308 may alleviate sepsis-induced ALI by inhibiting pyroptosis in macrophages." (PMID 39224841, 2024). "This study aims at investigating the effect of HSPA8 signal activation in AECs on sepsis-induced lung injury, as well as exploring whether HSPA8 is involved in the regulation of E3 ubiquitin ligase SKP2 and NLRP3 inflammasome." (PMID 38698431, 2024). "NLRP3 does not recruit phagocytes, as demonstrated in NLRP3-deleted mice undergoing polymicrobial sepsis after a CLP." (PMID 38256033, 2024). "The effects of ADAR1 on macrophage pyroptosis were verified in LPS-exposed RAW264.7 cells, and further experiments revealed that the miR-21/A20/NLRP3 signalling pathway was involved in the regulation of macrophage pyroptosis by ADAR1, impacting the cell survival state in sepsis." (PMID 38169584, 2024). "The findings revealed that TAN mitigated sepsis-induced ALI in mice through various pathways, primarily by inhibiting ROS-mediated activation of the NLRP3 inflammasome and modulating the polo-like kinase 1 (PLK1)/AMPK/dynamin-related protein 1(DRP1) signaling pathway." (PMID 38675431, 2024). "In a pregnancy‐induced sepsis model, Parabacteroides merdae promoted macrophage pyroptosis by upregulating the Flavin mononucleotide (FMN)–Heterogeneous nuclear ribonucleoprotein U‐like 2 (hnRNPUL2)–NLRP3 signaling axis." (PMID 39568773, 2024). "Thus, our findings for the first time revealed the immunological role of YOD1 in regulating NLRP3 inflammasome activation and coagulation in MRSA sepsis, and also provided a potential therapeutic target to treat sepsis-induced DIC." (PMID 38789414, 2024). "Based on these preliminary results, we inferred that the NLRP3 inflammasome may play a partial role in the polarization of M1 macrophages in FGF2 knockout macrophages and sepsis-induced acute lung injury." (PMID 39436561, 2024). "In conclusion, this study reveals that a high degree of mitophagy may predict a good outcome of sepsis, and PHB1 is a key NLRP3 inflammasome regulator via mitophagy in inflammatory diseases such as sepsis." (PMID 37359543, 2023). "In addition, Zhang W showed that carbon monoxide‐releasing molecules inhibit the activation of NLRP3 inflammasome by blocking the interaction between NLRP3 inflammasome and adaptive protein ASC, thus alleviating myocardial dysfunction in sepsis mice." (PMID 37904696, 2023). "According to the latest research, LPS or polymicrobial sepsis-induced mortality in CD38−/− mice were markedly augmented compared with wild types, and CD38−/− macrophages displayed markedly increased activation of NF-κB and NLRP3." (PMID 36998049, 2023). "In conclusion, Sirt3 is an important regulatory factor involved in acute lung injury in sepsis, we found that PD can significantly improve sepsis ALI, and its mechanism is related to the regulation of Sirt3/NLRP3 signal pathway, and the deeper mechanism needs to be further studied." (PMID 37494665, 2023). "The NLRP3/caspase‐1 signaling pathway regulates pyroptosis in a variety of diseases including sepsis, triple‐negative breast cancer, and myocardial ischemia/reperfusion." (PMID 37102651, 2023). "The results showed that the activation of NLRP3 was more intense in patients with sepsis than in non-septic patients, and the NLRP3 expression was significantly higher on day 7 in patients with sepsis who survived." (PMID 35967871, 2022). "The expression of key inflammasome proteins NLRP3 and caspase-1 and pyroptosis-related proteins GSDMD, IL-1β, and IL-18 was decreased, suggesting that inhibition of pyroptosis also alleviated lung injury in mice with sepsis." (PMID 35188436, 2022). "In a sepsis mouse model, GYY4137 treatment attenuated sepsis-induced cardiac dysfunction in WT but not Nlrp3 KO mice, suggesting that GYY4137 inhibited the inflammasome pathway." (PMID 36139861, 2022).